PIP5K1P1 (phosphatidylinositol-4-phosphate 5-kinase type 1 pseudogene 1)
Synonyms: MGC26597
Gene: Processed pseudogene on chromosome 6 (7,986,537 to 7,988,192, forward strand). Ensembl gene ENSG00000219294.
Diseases named in the same sentence as PIP5K1P1 in open-access papers:
PIP5K1P1 is named in the same sentence as 3 diseases in open-access papers, as found by Europe PMC text mining. Sharing a sentence is not in itself a finding about the gene and the disease. The quoted sentences say what the papers report.
cancer (1 paper, 2024). A tumor composed of atypical neoplastic, often pleomorphic cells that invade other tissues. "The result showed that PIP5K1P1 had important significance in evaluating the prognosis of patients with some types of cancer." (PMID 39170694, 2024). "The results of PCR showed that the mRNA expression levels of PIP5K1P1, PTTG3P, and SNORD15B in the cancer cells were significantly higher than those in normal cells." (PMID 39170694, 2024).
PIP5K1P1 also shares sentences with these, for which no sentence is quoted: prion disease (1 paper); stomach cancer (1).